RNU7-155P (RNA, U7 small nuclear 155 pseudogene)
Gene: Small nuclear RNA gene on chromosome 17 (71,298,156 to 71,298,218, reverse strand). Ensembl gene ENSG00000238759.
Homologues: Orthologues: chimpanzee U7 (98% identical), macaque U7 (84% identical). Paralogues in human: RNU7-35P (78% identical), RNU7-19P (76% identical), RNU7-1 (75% identical), RNU7-18P (75% identical), RNU7-48P (75% identical), RNU7-73P (75% identical), RNU7-85P (75% identical), RNU7-104P (73% identical), RNU7-10P (73% identical), RNU7-113P (73% identical), RNU7-12P (73% identical), RNU7-130P (73% identical), and 141 more.